RNY1P8 (RNY1 pseudogene 8)
Gene: Miscellaneous RNA gene on chromosome 13 (73,227,147 to 73,227,260, forward strand). Ensembl gene ENSG00000206697.
Homologues: Orthologues: chimpanzee Y_RNA (100% identical), guinea pig Y_RNA (90% identical), macaque Y_RNA (90% identical). Paralogues in human: RNY1 (89% identical), Y_RNA (88% identical), Y_RNA (87% identical), Y_RNA (86% identical), Y_RNA (85% identical), RNY1P11 (84% identical), Y_RNA (84% identical), Y_RNA (83% identical), Y_RNA (82% identical), RNY1P10 (82% identical), RNY1P5 (81% identical), Y_RNA (81% identical), and 96 more.